CTLA4 (cytotoxic T-lymphocyte associated protein 4)
Diseases named in the same sentence as CTLA4 in open-access papers (continued):
Sharing a sentence is not in itself a finding about the gene and the disease.
melanoma (continued). "It is a fully human anti-CTLA4 (IgG1) monoclonal antibody that has been shown to improve the long-term survival of melanoma patients." (PMID 37828948, 2023). "Using the B16 melanoma tumor model we observed similar response/resistance to combination anti-PD-1/CTLA-4 treatment in the KP lung model, as well as infiltration of Ly6C+ monocytes." (PMID 37449205, 2023). "While there are several new immunotherapies available for melanoma treatment, such as PD-1, PD-L1, and CTLA-4 inhibitors, these approaches are only effective for a small fraction of patients." (PMID 37422626, 2023). "Patients with malignant melanoma have been shown to achieve prolonged remission with the anti-CTLA-4 antibodies ipilimumab or tremelimumab." (PMID 37993258, 2023). "The NIBIT-M4 was a phase Ib, dose-escalation trial in patients with advanced melanoma of the hypomethylating agent guadecitabine combined with the anti-CTLA-4 antibody ipilimumab that followed a traditional 3 + 3 design (NCT02608437)." (PMID 37739939, 2023). "This association between clinical benefit and tumor mutational burden (TMB) was first shown with ipilimumab (anti-CTLA-4) in advanced melanoma patients." (PMID 36831435, 2023). "With the aim of addressing the lack of specific STS groups treated with immunotherapy, we introduced an independent melanoma cohort receiving a combination therapy of PD-1 and CTLA-4 blockade." (PMID 37408763, 2023). "The Eastern Cooperative Oncology Group (ECOG)-1609 (stage IIIB-IV melanoma) trial reported increased relapse-free survival (RFS) with adjuvant anti-CTLA-4 therapies versus high-dose interferon-based therapies (interferon-alfa-2b)." (PMID 36980641, 2023). "As such, monoclonal antibodies targeting either the PD-1 or the CTLA-4 protein are currently deemed as the standard of care in the treatment of advanced melanoma." (PMID 36428582, 2022). "Paradigm-shifting ICBs have brought great promises to patients with advanced melanoma, a tumor type that had been largely incurable until the approval of anti-CTLA-4 in 2011." (PMID 36008408, 2022). "In the Nathanson dataset, melanoma patients with high TIIClnc signature scores had prolonged survival time, and melanoma patients with high TIIClnc signature scores tended to respond to anti-CTLA-4 immunotherapy." (PMID 35966587, 2022). "Several genomic characteristics including high neoantigen load, high mutational load, and tumor clonality have been revealed to be predictive of a favorable response to anti-CTLA-4 therapy in melanoma." (PMID 35990677, 2022). "Melanoma cells resistant to anti-PD-1, anti-PD-L1 and anti-CTLA-4 immunotherapy show increased OXPHOS activity." (PMID 36612059, 2022). "Increasing evidence has shown that the combination of ipilimumab (CTLA-4 inhibitor) and nivolumab (PD-1 inhibitor) achieved better long-term outcomes in treating melanoma." (PMID 36499102, 2022). "Studies were next undertaken to determine if the expression of inhibitory ICP, such as CTLA-4, were altered by the melanoma lung metastasis." (PMID 36618349, 2022). "A phase II trial investigated the combination of TriMixDC-MEL (autologous monocyte-derived dendritic cells electroporated with synthetic mRNA) and ipilimumab (CTLA-4 blocking monoclonal antibody) in patients with pretreated advanced melanoma." (PMID 36569935, 2022). "CTLA-4 blockade has shown durable results in many types of cancer including melanoma, NSCLC, and renal cell carcinoma (RCC), possibly secondary to intratumoral Treg depletion." (PMID 35690784, 2022). "Using flow cytometry analyses, we observed that the CTLA-4 mAb led to a marked reduction in CD4+CD25+FoxP3+ Tregs in melanoma, consistent with early studies." (PMID 36050478, 2022). "We then validated the prediction power of this signature using 411 samples compiled from 6 melanoma cohorts 16,68–72, in which patients were treated with anti-PD-1 therapy alone or in combination with anti-CTLA-4 therapy." (PMID 35013211, 2022).
melanoma (continued). "Using subclass mapping, we compared the transcriptome profiles of two GC subclasses separated by FRLSG with another published dataset containing 47 patients with melanoma who received anti-PD-1 and anti-CTLA4 immunotherapy treatment." (PMID 35969182, 2022). "Our previous work using the syngeneic IFNγR1KD melanoma model identified a theretofore unreported role of tumor-intrinsic IFN-γ signaling in anti-CTLA-4 response." (PMID 36008408, 2022). "A previous study reported increased expression of Ki-67 by CD4+ and CD8+ T cells in patients with melanoma who received anti-CTLA-4 ipilimumab." (PMID 35514996, 2022). "Since then, inhibitors against the CTLA-4 and PD-1 immune checkpoints have revolutionized the treatment of not only melanoma, but also malignant tumors such as non-small cell lung cancer (NSCLC), renal cell carcinoma (RCC), and Hodgkin’s lymphoma." (PMID 35140720, 2022). "When RT and anti-CTLA-4 were combined, B78 tumor growth was reduced, but the response was still limited in this immunologically “cold” melanoma tumor model." (PMID 35999216, 2022). "The optimal anti-tumor effects of anti-CTLA-4 antibody therapy required specific Bacteroides species including Bacteroides thetaiotaomicron and Bacteroides fragilis in mice and humans with melanoma." (PMID 35514996, 2022). "In keeping with reported ICB resistance in tumors with impaired IFN-γ signaling, IFNγR1KO melanomas did not respond to anti-CTLA-4 treatment and continued to grow, whereas scrambled control melanomas were suppressed by anti-CTLA-4." (PMID 36008408, 2022). "To assess the impact of BET inhibition in vivo we treated B16-F10 melanoma bearing mice with anti-CTLA4 and anti-PD1 antibodies, to ensure better immunotherapy effects than by PD1 inhibition." (PMID 34753889, 2022). "For example, the anti-PD-1 monoclonal antibodies nivolumab and pembrolizumab and the anti-CTLA-4 antibody ipilimumab are being tested in clinical trials to treat melanoma." (PMID 36341437, 2022). "It has been shown that the combination of mch1N11 with the checkpoint inhibitors, anti-CTLA-4 or anti-PD-1 is superior to anti-CTLA-4 or anti-PD-1 alone in a melanoma mouse model." (PMID 35626139, 2022). "Translating these findings to the clinic, a recent phase Ib trial that combined HMA treatment with anti-CTLA-4 in patients with melanoma showed promising results, including improved immune activation and antitumor activity." (PMID 35838045, 2022). "Ipilimumab, a human IgG1 monoclonal antibody (mAb) against CTLA-4, was the first treatment approved for melanoma in 2010." (PMID 36648843, 2022). "In mouse melanoma models, immunotherapy with anti-CTLA-4 antibodies leads to increased expression of PRC2 components including EZH2 and upregulation of PD-L1, which together help tumour cells to evade the immune response despite the treatment." (PMID 35459932, 2022). "The introduction of B-RAF inhibitors and anti-CTLA4 and anti-PD-1/PD-L1 immunotherapies into standard of care brought measurable increases in the overall survival across all stages of melanoma." (PMID 36076924, 2022). "Eight patients, all with melanoma, received at least one more treatment with a different immune checkpoint inhibitor (3 with a CTLA-4 inhibitor and 5 with a PD-1 inhibitor)." (PMID 34164709, 2022). "The CHECKMATE 238 trial demonstrated that nivolumab can significantly extend RFS and DMFS even compared with the then-celebrated CTLA-4 inhibitor ipilimumab in stage IIIB/C or IV disease-free melanoma patients." (PMID 36678538, 2022). "It has been confirmed that the TIDE score predicts the outcome of melanoma patients treated with first-line anti-PD1 or anti-CTLA4 antibodies more accurately than other biomarkers, such as PD-L1 level and mutation load." (PMID 36159976, 2022). "In 2014, the FDA approved ipilimumab, a mAb targeting CTLA-4, for the treatment of melanoma; it significantly improved patient survival." (PMID 36304470, 2022).
melanoma (continued). "This led to a phase 1 trial that evaluated the use of TNFi in combination with ICIs (CTLA-4 and PD-1 inhibitors combination) for the treatment of melanoma." (PMID 36081549, 2022). "Data analysis was performed using the Samstein2018 cohort with 75 advanced melanoma patients who received anti-CTLA-4 therapy, and the results showed that 17 patients (22.7%) harbored HRR mutations (HRRmut)." (PMID 35990677, 2022). "The immune checkpoints’ expression has a role in immune escape via inhibiting the T-cell response, and immune checkpoint inhibitors have been widely used for melanoma, especially anti-CTLA4 and anti-PD-1 antibodies." (PMID 35899194, 2022). "In the clinic, dual blockade of CTLA-4 and PD-1 can achieve a more effective anti-tumour immune response in melanoma as both the CTLA-4 and PD-1 axes inhibit T cell activation and function using non-redundant mechanisms." (PMID 35366537, 2022). "Breast cancer, colon cancer, and melanoma cell lines were observed to grow less rapidly when curcumin, an NF-κB inhibitor, was combined with anti-CTLA-4 checkpoint suppression therapy." (PMID 36363529, 2022). "ICIs targeting PD-1 and CTLA4 have demonstrated significant activity in solid tumors, such as melanomas, non-small-cell lung cancer (NSCLC), and renal cell carcinoma." (PMID 35207516, 2022). "Similar to the approach described here, flow cytometric protocols for immune cell profiling were already used to identify checkpoint-related complications in melanoma patients receiving combined PD-1/CTLA-4 blockade." (PMID 35565343, 2022). "The AUC of the DLAT prediction model achieved 1.00 in Zhao glioblastoma (PD-1) and 0.80 in Nathanson melanoma (CTLA4)." (PMID 36581992, 2022). "In the melanoma cohort 15 patients had received both an anti-CTLA4 and an anti-PD-1/PD-L1, 16 patients had received an anti-PD-1/PD-L1, and 5 patients had received an anti-CTLA4." (PMID 35983060, 2022). "Because there was no immunotherapy information in the TCGA-SARC cohort, a cohort of melanoma patients treated with a combination of anti-PD-1 and anti-CTLA-4 was introduced." (PMID 35663937, 2022). "Shared T cell clones in the tumor, heart, and skeletal muscle were found in melanoma patients, who died from fatal myocarditis and myositis after treatment with anti-CTLA-4/PD-1 mAbs." (PMID 35432346, 2022). "Combined blockade of PD-1 and CTLA-4 is effective against melanoma and renal cell carcinoma as it can enhance the effector function of CD8+ tumor-infiltrating lymphocytes (TILs) by increasing CD28 costimulation." (PMID 35326731, 2022). "Due to these promising clinical studies, monoclonal antibodies against CTLA4 or PD-1 were eventually approved for treating various cancers including melanoma, lung cancer, kidney cancer and breast cancer." (PMID 35372044, 2022). "The treatment landscape of multiple cancers including melanoma has been revolutionized by ICIs, such as anti-PD-L1, anti-PD-1 and anti-CTLA4." (PMID 36733353, 2022). "The efficacy of anti-CTLA-4 can be enhanced when the ICOS pathway is simultaneously activated in melanoma and prostate cancer mouse models." (PMID 35326731, 2022). "BRAF and MEK inhibitors improve clinical outcomes, and anti-PD1 therapy demonstrates better results than chemotherapy or anti-CTLA4 therapy in terms of the survival of patients with advanced melanoma." (PMID 36844955, 2022). "An example of enhanced efficacy with combination therapy is the use of anti-CTLA-4 and anti-PD-1, which results in higher response rates and improved survival in melanoma patients." (PMID 36304470, 2022). "In a B16 melanoma model, mice treated with CTLA-4 blockade and GVAX vaccination 71 were monitored longitudinally by CD8+ PET imaging once a week for four weeks." (PMID 35223381, 2022). "Further, we describe the mode of action of ICI aimed at counteracting the anti-inflammatory effects of IC, which in the case of anti-CTLA-4 and anti-PD-1 have been granted early approval for melanoma treatment." (PMID 35406483, 2022).
melanoma (continued). "The immunotherapy approach used was closely related to tumor type, with the majority of patients receiving anti-CTLA-4 antibodies being treated for melanoma, with similar results observed in the combination (anti-PD-L1/PD-1 and anti-CTLA-4) group." (PMID 35798829, 2022). "The antibodies used in anti-melanoma immunotherapy target so called ‘immune checkpoints’: cytotoxic T-lymphocyte antigen-4 (CTLA-4) and programmed death-1 (PD-1), receptors on the surface of activated T cells." (PMID 35158770, 2022). "Analysis of the gene expression of melanoma tissues during CTLA-4 and high dose IFN-α2b combination therapy revealed a pro-inflammatory gene signature as a predictor of response and efficacy." (PMID 35269844, 2022). "Ipilimumab (Ipi), a monoclonal antibody against the human CTLA-4, has proven to be one of the most effective immunotherapy drugs for melanoma therapy, with a clinical response rate of only 10%." (PMID 36012593, 2022). "A recent meta‐analysis reported more treatment benefits of immunotherapy, particularly CTLA‐4 inhibitors, in men than in women with advanced cancers, excluding melanoma." (PMID 35822692, 2022). "Using PD-1/PD-L1 and/or CTLA-4 inhibitors results in much longer overall survival rates, especially among melanoma, lung and bladder cancer patients." (PMID 35459932, 2022). "A study of patients with melanoma found that incidence of colitis was lower in those with rich Bacteroidetes following the treatment of anti-CTLA-4 antibody ipilimumab." (PMID 37674988, 2022). "Currently, three immune checkpoint inhibitors are used to treat melanoma, including the anti-CTLA-4 antibody ipilimumab and the two anti-PD-1 antibodies nivolumab and pembrolizumab." (PMID 35401191, 2022). "Between 2010 and 2022, CTLA-4 blockade has always been an important topic in melanoma, while PD-1 blockade has become more popular since 2016." (PMID 36698407, 2022). "Another study illustrated enhanced rejection of B16-OVA melanoma cells using ovalbumin-producing Salmonella and αPD-L1 compared to Salmonella alone or combination of PD-L1 and CTLA-4 inhibitors through enhancing the expansion of CD8+ T cells." (PMID 36605208, 2022). "Intestinal Bifidobacterium pseudolongum-driven inosine metabolites promote Th1 differentiation and activation, shaping a robust immune response following anti-CTLA-4 and anti-PD-L1 immunotherapy in preclinical models of melanoma and CRC." (PMID 35892821, 2022). "Among advanced melanoma that respond to CTLA-4 or PD-1 blockade therapy, approximately one-quarter to one-third of patients will relapse over time." (PMID 35000592, 2022). "Combination therapy with anti–CTLA-4 and anti–PD-1 has been approved or in clinical trials for certain cancers including melanoma." (PMID 35515106, 2022). "In clusters 2 and 3 that rely on OXPHOS, OXPHOS inhibitors would increase ICI sensibility in melanoma patients that progressed with PD-1 and CTLA4 blockade and in melanoma brain metastases that rely on OXPHOS." (PMID 36119118, 2022). "In a retrospective study on melanoma and prostate cancer patients, CTLA-4 blockade has been described to support a vigorous renovation of the TCR repertoire by inducing the occurrence of an overall enlarged repertoire diversity." (PMID 36550555, 2022). "As there was no information about immunotherapy in the TCGA-SARC cohort, a cohort of melanoma patients treated with the combination of anti-PD-1 and anti-CTLA-4 was utilized." (PMID 35860263, 2022). "Initial investigations on the effect of baseline TCR repertoire on melanoma patients treated with anti-CTLA-4 or anti-PD-1, showed that a high diversity in peripheral blood, was associated with good clinical outcomes." (PMID 36550555, 2022). "Combination therapy of anti-CTLA-4 and anti-PD-1 antibodies is effective in mouse models and in patients with melanoma, renal cell carcinoma (RCC), and lung cancer." (PMID 35806328, 2022).
melanoma (continued). "The first ICI receiving FDA approval in 2011 was Ipilimumab, an anti-CTLA-4 for patients with advanced melanoma." (PMID 35008422, 2022). "In a clinical study with 26 melanoma patients who received anti-CTLA4 Abs treatment, Bacteroides spp." (PMID 36429112, 2022). "As a recognized checkpoint in the immune system, CTLA-4 has been extensively investigated as an immunotherapeutic target for a variety of malignancies, including melanoma, prostate cancer, and hepatocellular cancer." (PMID 35585975, 2022). "A measles OVT was developed to express CTLA-4 antibodies and showed promising results in human melanoma xenografts." (PMID 35515106, 2022). "Immune checkpoint inhibitors (ICI), which block the inhibitory receptors PD-1 and CTLA-4 on T cells, have transformed the treatment of advanced melanoma." (PMID 35565329, 2022). "In line with our PDAC findings, ΔS melanoma growth was impaired following anti-CTLA4 treatment, whereas ΔL tumors were largely refractory." (PMID 36344707, 2022). "Superior therapeutic efficacy with combination immune checkpoint blockade was demonstrated in clinical trials of anti-PD-1 and anti-CTLA-4 for melanoma including improved long-term survival but at a cost of higher rates of immune-related toxicities." (PMID 35123267, 2022). "In 2011, Ipilimumab (anti-cytotoxic T-lymphocyte antigen 4 or anti CTLA-4) was the first ICI to receive FDA approval after demonstrating positive clinical outcomes in melanoma patients." (PMID 36072595, 2022). "Melanoma immunotherapies using immune checkpoint blocking antibodies for the PD-1/PD-L1 axis and CTLA-4 axis have become a robust strategy for improving clinical outcomes." (PMID 36428680, 2022). "It is also worth mentioning that the radiation-induced abscopal effect observed in melanoma patients can be significantly enhanced when used in combination with immune checkpoint blockade (e.g., anti-CTLA4 and anti-PD1)." (PMID 36297510, 2022). "PRMT7 inhibition induced viral mimicry and sensitized therapy-resistant B16F10 melanoma tumors to CTLA-4 and PD-1 treatment in vivo." (PMID 36497341, 2022). "After C57BL/6 mice were challenged with B16 melanoma cells or vehicle control, the expression of CTLA-4 was evaluated 2 weeks later." (PMID 36618349, 2022). "We compared the expression matrix of high and low risk groups to that of a melanoma dataset in which patients underwent anti-PD1 and anti-CTLA4 therapies." (PMID 35372082, 2022). "Preclinical studies have shown that the combination of VEGFR inhibitor Axitinib and anti-CTLA-4 can enhance the antigen-presenting ability of DC to promote T cell proliferation in a mouse melanoma model." (PMID 36304470, 2022). "We first evaluated the incidence of hepatitis and other immune-related adverse events (irAE) in a prospectively recruited discovery cohort of n = 39 patients after initiation of anti-PD-1 & anti-CTLA4 therapy due to advanced melanoma over a period of 100 days." (PMID 36503532, 2022). "Here we demonstrate that CHI3L1 inhibits the expression of ICOS, ICOSL and CD28 while stimulating CTLA-4 and the B7 moieties in melanoma lung metastasis." (PMID 36618349, 2022). "A syngeneic mouse model carrying B16-F10 melanoma cells was treated with PD-1 and CTLA4 inhibitors, which was curative." (PMID 34753889, 2022). "We analyzed publicly available RNA-Seq data from 73 melanoma patients treated with standard-of-care single-agent nivolumab or pembrolizumab (n = 41) or combination anti-PD-1 + anti-CTLA-4 (n = 32; PRJEB23709)." (PMID 36099049, 2022). "TMB has been shown to be a biomarker for immune checkpoint inhibitors (ICIs) in melanoma, and high TMB acts via anti-CTLA-4 and anti-PD-1 in melanoma and non-small cell lung cancer." (PMID 36135086, 2022). "NK cell activation markers and response to anti-CTLA-4 therapy have been positively correlated in melanoma patients." (PMID 35326731, 2022).